CADM3 (cell adhesion molecule 3)
Description:
Involved in cell-cell adhesion. Has both calcium-independent homophilic cell-cell adhesion activity and calcium-independent heterophilic cell-cell adhesion activity with IGSF4, NECTIN1 and NECTIN3. Interaction with EPB41L1 may regulate structure or function of cell-cell junctions (By similarity).
Synonyms: IgSF4B; NECL-1; SynCAM3; TSLL1; NECL1; BIgR; FLJ10698; CMT2FF
Tractability: Antibody: UniProt places it where antibodies can reach, with high confidence; its Gene Ontology location is reachable by antibodies, with high confidence; UniProt predicts a signal peptide or a membrane-spanning region. PROTAC: its protein half-life has been measured.
Gene: Protein-coding gene on chromosome 1 (159,171,609 to 159,203,313, forward strand). Ensembl gene ENSG00000162706.
Subcellular location: Cell membrane; Cell junction
Pathways (Reactome):
Cell-Cell communication: Adherens junctions interactions; Nectin/Necl trans heterodimerization
Gene Ontology:
Molecular function: protein binding; protein homodimerization activity
Biological process: heterophilic cell-cell adhesion; homophilic cell-cell adhesion
Cellular component: anchoring junction; plasma membrane; cell-cell junction; presynaptic membrane; parallel fiber to Purkinje cell synapse
Genetic constraint (gnomAD): Loss-of-function variants: 10 observed, 44.58 expected, observed/expected ratio (o/e) 0.22, 90% interval 0.14 to 0.38. The upper end of that interval is the gene's LOEUF score, 0.38, which puts it in group 1 of 6, group 1 being the genes least tolerant of losing a copy. Missense variants: 419 observed, 516.39 expected, observed/expected ratio (o/e) 0.81, 90% interval 0.75 to 0.88. Synonymous variants: 206 observed, 205.09 expected, observed/expected ratio (o/e) 1, 90% interval 0.9 to 1.13.
Gene-disease validity (ClinGen):
ClinGen rates the evidence that CADM3 causes each of these diseases.
Charcot-Marie-Tooth disease, axonal, type 2FF (autosomal dominant): Moderate.
Homologues: Orthologues: chimpanzee CADM3 (99% identical), macaque CADM3 (99% identical), pig CADM3 (96% identical), mouse Cadm3 (95% identical), rat Cadm3 (94% identical), guinea pig CADM3 (94% identical), dog CADM3 (91% identical), rabbit CADM3 (89% identical), tropical clawed frog cadm3 (61% identical), zebrafish cadm3 (53% identical), Drosophila melanogaster Fas3 (20% identical). Paralogues in human: CADM2 (50% identical), CADM1 (39% identical), CADM4 (34% identical), NECTIN1 (25% identical), NECTIN3 (24% identical), NECTIN4 (23% identical), NECTIN2 (22% identical), PVR (21% identical), CRTAM (16% identical), CD226 (14% identical), CD200 (11% identical), TIGIT (10% identical), and 2 more.
Diseases named in the same sentence as CADM3 in open-access papers:
CADM3 is named in the same sentence as 23 diseases in open-access papers, as found by Europe PMC text mining. Sharing a sentence is not in itself a finding about the gene and the disease. The quoted sentences say what the papers report.
glioma (3 papers, 2022 to 2023). A benign or malignant brain and spinal cord tumor that arises from glial cells (astrocytes, oligodendrocytes, ependymal cells). "CADM3 has been implicated in tumorigenesis in previous studies, displaying tumour-suppressive properties in glioma and several other types of cancer 18-20." (PMID 35198079, 2022).
breast carcinoma (2 papers, 2012 to 2024). "Our research first analyzed the expression and prognostic value of CADM3 in using clinical breast cancer samples from patients and multiple bioinformatics databases." (PMID 38515057, 2024). "However, there are few studies on CADM3 in tumors, and how it works in breast cancer (BC) remains unclear." (PMID 38515057, 2024). "In conclusion, the upregulation of CADM3 was correlated with favorable prognosis, immune infiltration and MAPK pathway in breast cancer patients." (PMID 38515057, 2024). "Therefore, we speculate that CADM3 inhibits PD-L1 expression in breast cancer cells by regulating ERK protein in the MAPK pathway, thereby reducing its binding to T cells, so that T cells are released and the weakened immune function of tumor cells is restored." (PMID 38515057, 2024). "In contrast to decreased TGFBI that has previously been associated with DCIS, decreased CADM3, DPT, and NID1 have not previously been linked to breast cancer." (PMID 23236365, 2012).
colon cancer (2 papers, 2012 to 2021). "CADM3 also known as nectin like protein 1 (Necl1) is a cell-cell adhesion molecule and has been reported to suppress tumorigenicity in colon cancer cells." (PMID 23236365, 2012).
gastric cancer (2 papers, 2023 to 2025). A primary or metastatic malignant neoplasm involving the stomach. "FABP4, a fatty acid‐binding protein, has been shown to inhibit CADM3 transcription by regulating PPAR‐γ, thereby promoting gastric cancer metastasis." (PMID 41152153, 2025).
Arthritis (1 paper, 2019). Inflammation of a joint. "Taken together, we demonstrate that both CNTN1 and CADM3 may be involved in intrathecal processes regulating pain also in arthritis patients." (PMID 30770760, 2019). "Taken together, we found that several proteins with inflammatory function were decreased in arthritis CSF after infliximab treatment, including proteins with additional neuro-immunomodulatory function such as FGG, CNTN1 and CADM3." (PMID 30770760, 2019).
autism (1 paper, 2016). Persistent deficits in social interaction and communication and interaction as well as a markedly restricted repertoire of activity and interest as well as repetitive patterns of behavior. "Three types of CvN unique genes were registered in the autism KB database: Cadm3 (cell adhesion molecule), Gpr83 (G protein-coupled receptor), and Acta1 (actin α1)." (PMID 27782041, 2016).
Charcot-Marie-Tooth disease (1 paper, 2025). An inherited degenerative disorder involving the peripheral nerves. "Recently, it has been reported that a CADM3 mutation inducing abnormal axon-glia interaction causes Charcot-Marie-Tooth disease which shares with ALS the impaired motor function." (PMID 40681694, 2025).
Lassa fever (1 paper, 2021). A viral hemorrhagic fever that is caused by the Lassa virus, which is transmitted by contact with infected rodents; it is characterized by fever, headache, malaise, myalgia, and hearing loss. "Genes involved in extracellular matrix and cell-adhesion were also modulated, particularly during fatal Lassa fever (NID1, TIMP3, ITGA11, TGM2, MMP8/9, OLFM4, PCDH20, and CADM3), as well as some others involved in coagulation (SERPIN, TFPI2) and apoptosis (CLU, BCL2L14)." (PMID 33398113, 2021).
lung carcinoma (1 paper, 2024). "CADM3 may also decrease the likelihood of developing lung cancer in the same manner." (PMID 39668834, 2024).
Obesity (1 paper, 2017). Accumulation of substantial excess body fat. "rs12075 (DARC/CADM3) that predicted MCP-1 also has potential pleiotropic effects on obesity-related traits based on a comprehensive search of Ensembl." (PMID 28819125, 2017).
ovarian carcinoma (1 paper, 2021). A malignant neoplasm originating from the surface ovarian epithelium. "Particularly, we examined if ANPEP (from EC2), CASP14 and CLEC2B (from EC3), CADM3 and NRBP2 (from EC4), and SPC25, ESCO2, and GTSE1 (from EC5) are responsible for ovarian cancer cell proliferation by the cell viability assay." (PMID 34459128, 2021). "Additionally, our study identified a number of novel markers, such as CASP14, CLEC2B, CADM3, NRBP2, SPC25, ESCO2, and GTSE1, which are upregulated in a cluster‐specific manner and critical for ovarian cancer cell proliferation and migration." (PMID 34459128, 2021).
Parkinson disease (1 paper, 2025). A progressive degenerative disorder of the central nervous system characterized by loss of dopamine producing neurons in the substantia nigra and the presence of Lewy bodies in the substantia nigra and locus coeruleus. "The research further demonstrated that the co-DEGs of GPR78, CADM3, and CACNA1E connect NETs with Parkinson’s disease and established a nomogram model for diagnosing PD based on these genes." (PMID 40469282, 2025).
polyarthritis (1 paper, 2022). "In cerebrospinal fluid from patients with polyarthritis, a downregulation of CADM3 has been reported following TNF-α blockage." (PMID 36080454, 2022).
retinal vein occlusion (1 paper, 2022). An occlusion of the retinal vein. "Our results strongly suggest that FKBP5 and CADM3 are corticosteroid-sensitive proteins in retinal vein occlusion, as the regulation of the proteins has been identified in two individual proteome studies of the DEX implant." (PMID 36080454, 2022). "We previously identified an upregulation of FKBP5 and a downregulation of CADM3 in a proteome study where the DEX implant intervention was studied in a model of experimental branch retinal vein occlusion (BRVO), a subtype in which a sector of the retina is affected by retinal vein occlusion." (PMID 36080454, 2022).
tumor (8 papers, 2019 to 2024). "A valuable diagnostic marker for this tumor is the SynCam3/CADM3 antibody, which is a highly specific and sensitive marker for these tumors based on the available studies as well as in our experience." (PMID 39264472, 2024). "CADM3 is a calcium-independent intercellular adhesion protein that has been reported to be a tumor suppressor gene." (PMID 37446311, 2023). "CADM3 is a calcium-independent intercellular adhesion protein that is also reported to be a tumor suppressor gene." (PMID 37446311, 2023). "According to the univariate analysis, a number of factors including CADM3 expression, molecular typing (PAM50), tumor status (T), and lymph node status (N) were notably related to OS, DFS, and MFS." (PMID 38515057, 2024). "Staining for CADM3, IGLON5, and TGFB1 was low in tumor tissue; staining for LEP and ABI3BP was medium in tumor tissue; staining for CD1B was high in tumor tissue." (PMID 34497681, 2021). "Cell Adhesion Molecule 1 (CADM1), CADM2, CADM3 and CADM4, serve as tumor suppressors and can inhibit cancer cell proliferation and induce apoptosis." (PMID 31480483, 2019). "No studies have explored HIST1H2BG’s potential as a tumor biomarker for CRC and low methylation level of CADM3 was associated with poor survival of CRC." (PMID 37446311, 2023). "Interestingly, when PDE9A, CADM3, and FNBP1 were used as co-predictors, they all showed low expression in tumor tissue, suggesting their potential use as biomarkers for predicting CRC." (PMID 37446311, 2023).
cancer (5 papers, 2019 to 2024). A tumor composed of atypical neoplastic, often pleomorphic cells that invade other tissues. "We found that CADM3 was significantly differentially expressed in 13 cancers, of which 11 were downregulated in cancer tissues, including BC." (PMID 38515057, 2024). "CADM3 and CADM4 were upregulated in most cancers, whereas NECTIN2 was downregulated in most cancers." (PMID 34925438, 2021).
CADM3 also shares sentences with these, for which no sentence is quoted: Alzheimer disease (1 paper); coronary atherosclerosis (1); infection (1); medulloblastoma (1); melanoma (1); retinoblastoma (1); spinal cord injury (1).